TLR8 (toll like receptor 8)
Diseases named in the same sentence as TLR8 in open-access papers (continued):
Sharing a sentence is not in itself a finding about the gene and the disease.
enteroviral infection (2 papers, 2019). "However, a number of studies have demonstrated that TLR7 and TLR8 can be induced upon enteroviral infection." (PMID 31117206, 2019). "Although the role of TLR7 and TLR8 have not been extensively studied during enterovirus infection, it is becoming clear that these PRRs may play key roles in the induction of proinflammatory cytokines." (PMID 31117206, 2019).
fibrosis (2 papers, 2021 to 2025). the formation of excess fibrous connective tissue in an organ or tissue in a reparative or reactive process. "The frequency of pDCs in BAL fluid correlates with severity of fibrosis on chest CT in SSc-ILD patients, while in SSc skin lesions, pDCs accumulate in perivascular regions and produce increased IFN-α and chemokine ligand 4 (CXCL4) via TLR8 and phosphoinositide 3-kinase-δ signaling." (PMID 33859634, 2021). "Also, TLR8 overexpression increased pDC skin infiltration and fibrosis in mice, whereas TLR8 inhibition, but not TLR7 inhibition, prevented fibrosis and alleviated skin fibrosis in established disease in the mouse model of bleomycin (BLM)-induced fibrosis." (PMID 40423726, 2025).
hepatitis C virus infection (2 papers, 2011 to 2025). A viral infection caused by the hepatitis C virus. "The TLR8 -129C > G rs3764879 variant was examined in individuals with hepatitis C virus infection by Wang and colleagues." (PMID 40531670, 2025).
Histiocytosis (2 papers, 2018 to 2023). An excessive number of histiocytes (tissue macrophages). "Moreover, human TLR8 expressed in Slc29a3−/−Tlr7−/− mice caused histiocytosis." (PMID 37462944, 2023). "TLR7 and TLR8 serve as metabolite sensors to activate lysosomal stress responses, which drive histiocytosis unless the stress is relieved." (PMID 37462944, 2023). "TLR8 drove histiocytosis in Slc29a3−/−Tlr7−/− mice and a TLR8 antagonist inhibited the survival of SLC29A3G208R/G208R monocytes in vitro." (PMID 37462944, 2023). "Two lines of evidence support the possibility that TLR7 and TLR8 drive histiocytosis in a cell-autonomous manner." (PMID 37462944, 2023). "We hypothesized that Guo, dGuo, and Urd accumulate in the compartments where TLR7 and TLR8 are localized and activate TLR7 and TLR8 to drive histiocytosis in SLC29A3 disorders." (PMID 37462944, 2023). "Second, macrophage-specific expression of human TLR8 by the Lyz2-Cre driver could drive histiocytosis in Slc29a3−/−TLR7−/− mice." (PMID 37462944, 2023). "Much less is known about histiocytosis by constitutive human TLR8 activation." (PMID 37462944, 2023). "Mouse TLR8 does not respond to nucleosides and ssRNAs, and negatively regulates TLR7, suggesting that mouse TLR8 might inhibit TLR7-dependent histiocytosis." (PMID 37462944, 2023). "However, TLR8 deficiency did not alter histiocytosis in Slc29a3−/− mice." (PMID 37462944, 2023). "Therefore, TLR8 did not impact histiocytosis in Slc29a3−/− mice." (PMID 37462944, 2023).
Intestinal inflammation (2 papers, 2011 to 2018). "This study demonstrates that TLR2, TLR4, TLR8, and TLR9 expression increases in active UC patients, and that the mRNA levels positively correlate with the severity of intestinal inflammation as well as with inflammatory cytokines." (PMID 22185629, 2011).
Klinefelter syndrome (2 papers, 2023 to 2024). A sex chromosome disorder caused by the presence of an extra X chromosome in the male karyotype. "Recently, it was demonstrated that the gene encoding TLR8, which is closely located to Tlr7, also escapes X-chromosome inactivation in immune cells in women and Klinefelter syndrome men." (PMID 38791389, 2024). "The close proximity between the two genes, and the homology and similarity of function between the encoded receptors, warranted investigating whether TLR8, mirroring TLR7, could be transcribed on the inactive X chromosome (Xi) of the immune cells of women and Klinefelter syndrome men." (PMID 37723501, 2023). "We unequivocally demonstrated that TLR8, like TLR7, escapes XCI in immune cells from female and Klinefelter syndrome males." (PMID 37723501, 2023).
Lyme disease (2 papers, 2012 to 2016). Lyme disease (named after the towns in the USA where the disease was first identified) is a bacterial infection caused by Borrelia burgdorferi. "In this regard, we recently provided evidence that transcription of IFN-β in human monocytes stimulated ex vivo with Borrelia burgdorferi, the Lyme disease spirochete, was dependent on phagocytosis and degradation of the bacterium and required signaling through TLR8." (PMID 22816000, 2012).
lymphoma (2 papers, 2014). A malignant (clonal) proliferation of B- lymphocytes or T- lymphocytes which involves the lymph nodes, bone marrow and/or extranodal sites. "Activating mutations in MyD88 have been described in human lymphomas, suggesting that constitutive human TLR7 or TLR8 signaling in our mice could be driving proliferation." (PMID 25229618, 2014). "Here we show that KSHV-miR-K-12-10b and miR-K-12-12* bind to TLR8 and this induces the increased secretion of the IL-6 and IL-10 by the cultured BCP1 clonal lymphoma cell line positive for KSHV." (PMID 25476907, 2014).
otitis media (2 papers, 2016 to 2021). Inflammation of the anatomical structures of the middle ear, which is most often caused by an infectious process. "In a study investigating a role for TLR8 in the pathophysiology of otitis media, an analysis of TLR8 polymorphisms in 381 AOM children revealed that TLR8 polymorphisms were associated with an increased susceptibility to recurrent rhinovirus infections." (PMID 34360632, 2021). "In males, the presence of the TLR8 minor allele C was associated with recurrent otitis media, which was present in 22 (68.8%) of the 32 minor allele C carriers vs. in 13 of the 33 (39.4%) major allele G carriers (p = 0.04)." (PMID 27498757, 2016). "In addition, we revealed a preliminary association between the presence of the TLR8 rs4207992 minor allele C and recurrent otitis media in males but not in females." (PMID 27498757, 2016).
pulmonary sarcoidosis (2 papers, 2024 to 2025). Sarcoidosis affecting the lung parenchyma. "CTSS, CYBB, FPR2, MNDA, TLR1, and TLR8 could be conducive to improving the diagnostic process and understanding the underlying mechanisms of pulmonary sarcoidosis, and were further verified in PBMC samples using qRT-PCR." (PMID 39364409, 2024). "CTSS, CYBB, FPR2, MNDA, TLR1, and TLR8 could be conducive to improving the diagnostic process and understanding the underlying mechanisms of pulmonary sarcoidosis." (PMID 39364409, 2024). "Among the top 13 biomarkers with an AUC > 0.90, plasma lysozyme (P61626, encoded by the LYZ gene) and toll-like receptor 8 (Q9NR97, encoded by the TLR8 gene) have been identified as diagnostic biomarkers specifically for pulmonary sarcoidosis 55 and cardiac sarcoidosis 56, respectively." (PMID 41279897, 2025).
pulpitis (2 papers, 2017 to 2020). Inflammation of the dental pulp. "In addition to investigating the possible regulatory mechanisms of DEGs, we screened key genes as biomarker candidates for the diagnosis of pulpitis, including PTPRC, CD86, CCL2, IL6, TLR8, MMP9, CXCL8 and ICAM1." (PMID 33046027, 2020). "Furthermore, deciduous pulps with pulpitis suffered higher expressions of proinflammatory cytokines (IL-6 and MCP-1) and innate immune response (TLR1, TLR2, TLR3, TLR6, and TLR8) than pulps without pulpitis." (PMID 28377925, 2017).
sarcoidosis (2 papers, 2024 to 2025). Sarcoidosis is a multisystemic disorder of unknown cause characterized by the formation of immune granulomas in involved organs. "In addition, our GO MF results showed that TLR8 was enriched for pattern recognition receptor activity, suggesting that the alteration of TLR8 activity may be involved in the pathogenesis of sarcoidosis." (PMID 39364409, 2024). "However, upregulation of SPP1 was more modest, and unlike NL and NXG macrophages, sarcoidosis lesional macrophages strongly overexpressed APOE, VAT1, TLR8, and ALDH1A1 among other genes." (PMID 39989459, 2025).
uveitis (2 papers, 2025). An inflammatory process affecting a part of or the entire uvea. "To identify core regulatory genes shared between AS and uveitis, we first intersected genes from WGCNA-derived disease-associated modules and cross-disease DEGs, yielding five candidate genes: SORL1, TLR8, HLX, SLC25A20, and IGSF6." (PMID 40929101, 2025). "For instance, metaDEGs of the uveitis only group comprise genes that are involved in the innate immune response, such as chemokine receptors (CX3CR1, CCR1, and CCR2), and Toll-like receptors (TLR4, TLR7, TLR8, and the TLR4 homologous receptor, CD180)." (PMID 40270958, 2025).
acute viral hepatitis (1 paper, 2014). "Nevertheless, our data might indicate that TLR8-mediated activation of intrahepatic immunity might also take place during other pathological conditions, e.g., acute viral hepatitis and hepatic flares during chronic viral hepatitis." (PMID 24967632, 2014).
allergic asthma (1 paper, 2010). A asthma with a basis in a pathological type I hypersensitivity reaction. "Moreover, recently published analysis of TLR8 polymorphism linked to allergic asthma, indicate importance of TLR8 in type 1 vs. type 2 immune response balance that has been also impaired in infants with severe RSV infection." (PMID 20946625, 2010).
Anosmia (1 paper, 2022). An inability to perceive odors. "in TLR8 gene (presence of anosmia = 71.4% vs. absence = 33.3%) and the p.Met129Thr in TRAF3 gene (presence of anosmia = 48.1% vs. absence = 23.7%)." (PMID 36228008, 2022). "Global analysis showed some variants associated with anosmia in IFHI1, TLR8, MAVS and TRAF3: this suggests that not only the severity of symptomatology but also even some very specific clinical manifestations depend on host genomic profiles." (PMID 36228008, 2022).
Anxiety (1 paper, 2021). Intense feelings of nervousness, tension, or panic often arise in response to interpersonal stresses. "Although Tlr7–/y knockout mice exhibit some behavioral abnormalities in terms of olfaction, anxiety, aggression and contextual fear memory, we cannot be sure if Tlr8 upregulation also influences the phenotype of Tlr7 knockout mice." (PMID 34211474, 2021).
atrial fibrillation (1 paper, 2023). A disorder characterized by an electrocardiographic finding of a supraventricular arrhythmia characterized by the replacement of consistent P waves by rapid oscillations or fibrillatory waves that vary in size, shape and timing and are accompanied by an irregular ventricular response. "A study reported that TLR8 was correlated with levels of IL6, IL1β, and a greater inflammatory response, which is an important mechanism that causes atrial fibrillation." (PMID 36671813, 2023).
B cell deficiency (1 paper, 2022). A broad classification of disorders where circulating numbers of B lymphocytes are decreased or ineffective. "Although TLR8 is expressed in myeloid cells, T cell activation and B cell deficiency develop, probably because of the cell non-autonomous mechanisms." (PMID 35812450, 2022).
Burkitt lymphoma (1 paper, 2020). A rare form of malignant mature B-cell non-Hodgkin lymphoma. "Ultimately, according to the obtained results, TLR8 signaling may be a potential target for Burkitt lymphoma therapy." (PMID 32257888, 2020).
cardiomyopathy (1 paper, 2018). A disease of the heart muscle or myocardium proper. "Moreover, it has been investigated by others that the Tlr8 has a significant prognostic impact in patients suffering from enterovirus-associated cardiomyopathy." (PMID 29538462, 2018).
cervical squamous cell carcinoma (1 paper, 2024). A squamous cell carcinoma arising from the cervical epithelium. "A trend toward TLR8 hyperexpression was observed when comparing patients with invasive cervical squamous cell carcinoma associated with active HPV infection and HPV−/LSIL (p = 0.0571)." (PMID 39273663, 2024).
chorioamnionitis (1 paper, 2012). A morphologic finding indicating inflammation of the fetal sac membranes. "For instance, of the 6 women with chorioamnionitis none had increased levels of TLR3, only 1 had increased levels of TLR7, and 2 for TLR8." (PMID 22848646, 2012).
chronic lung disease (1 paper, 2018). According to the definitions of the American and British Thoracic Societies, including pulmonary functional tests, X-rays, and CT scans for items such as fibrosis, bronchiectasis, bullae, emphysema, nodular or lymphomatous abnormalities. "Based on the hypothesis on the origin of chronic lung diseases like COPD during the early life events, we could detect three novel (HJURP, MCRS1 and TLR8) COPD candidate genes and replicate the findings in 17 other studies using a mouse-human translational datamining approach." (PMID 29871630, 2018).
common variable immunodeficiency (1 paper, 2023). "In this study, we aim to unravel the intricate involvement of TLR2, TLR4, TLR3, TLR7, TLR8, and TLR9 in the immunopathogenesis of common variable immunodeficiency—CVID (as PID)—and chronic lymphocytic leukemia—CLL (as SID)." (PMID 37626865, 2023).
Dysmenorrhea (1 paper, 2017). Pain during menstruation that interferes with daily activities. "After statistical analysis confirmed that: The gene expression of TLRS (TLRS = TLR1 + TLR2 + TLR3 + TLR4 + TLR5 + TLR6 + TLR7 + TLR8 + TLR9) in severe and moderate dysmenorrhea group was significantly higher than that in minimal dysmenorrhea group in EU and EC (P < 0.05 or P < 0.01)." (PMID 28779087, 2017).
E. coli infection (1 paper, 2019). "With P. aeruginosa infection, the TLR8 inhibitor impaired the production of IL-12p70 and IL-1β, while with E. coli infection the inhibitor had less effect that varied depending on the strain and conditions." (PMID 31214180, 2019). "This revealed significant and non-redundant contribution of TLR8 to cytokine production during E. coli infection." (PMID 31214180, 2019).
end-stage renal disease (1 paper, 2015).
glioblastoma (1 paper, 2009). The most malignant astrocytic tumor (WHO grade IV). "Synthetic siRNA duplexes have now been show to activate PKR in glioblastoma cells, RIG-I in glioblastoma cells and primary human monocytes, TLR3 in HEK293 cells and murine models, TLR7 in murine leukocytes and human plasmacytoid dendritic cells, and TLR8 in human monocytes." (PMID 19630977, 2009).
glomerular diseases (1 paper, 2014). "In conclusion, we showed that members of the TLR family and the TLR8-mediated pathway in particular correlate with podocyte injury in murine autoimmune GN, suggesting that TLR8 is a novel therapeutic and diagnostic target for mouse and human glomerular diseases." (PMID 25468389, 2014).
Granuloma (1 paper, 2024). A compact, organized collection of mature mononuclear phagocytes, which may be but is not necessarily accompanied by accessory features such as necrosis. "Adverse effects, including fever, chronic inflammation, and granuloma, were reported using a combination of TLR1/2, TLR9, and TLR8 agonists in swine." (PMID 39355141, 2024). "One of the studies, reported adverse effects, including fever, chronic inflammation, and granuloma in the use of TLR1/2, TLR9, and TLR8 agonists combination administered intramuscularly in swine." (PMID 39355141, 2024).
head and neck cancer (1 paper, 2021). A primary or metastatic malignant neoplasm affecting the head and neck. "The combination of cetuximab with either TLR3 or TLR8 stimulation induced increased NK-cell-mediated ADCC of head and neck cancer cells compared to cetuximab alone." (PMID 34681717, 2021).
hemorrhagic fever (1 paper, 2015). An infectious disease caused by certain viruses or bacteria that can damage the walls of tiny blood vessels, making them leak, and can hamper the blood's ability to clot and cause severe, life-threatening illness. "SNPs significantly associated with eye disease included three different polymorphisms TLR8 and hemorrhagic fever symptoms associated with TLR3, TLR7, TLR8 and MyD88." (PMID 25756647, 2015).
hepatoma (1 paper, 2021). "TLR3, TLR7, and TLR8 protein were undetectable in most hepatoma cell lines and A549 epithelial cells as measured by surface antibody staining." (PMID 34831243, 2021). "Next, we addressed expression levels of the endosomal RNA sensors TLR3, TLR7, and TLR8 as well as the TLR3 adaptor TIR domain-containing adaptor protein 1 (TICAM1 or TRIF) in hepatoma cell lines and primary hepatocytes." (PMID 34831243, 2021).
Hyperglycemia (1 paper, 2016). An increased concentration of glucose in the blood. "It is not clear whether hyperglycemia could upregulate TLR8 expression, and a few studies both in humans and mice have shown the link between hyperglycemia and TLR2/4 induction and upregulation." (PMID 27980459, 2016).
hyperlipidemia (1 paper, 2025). "Stratification by disease status and hyperlipidemia revealed that MCL1, F13A1, TLR8, and TAGAP were significantly upregulated in patients with both AS and hyperlipidemia compared with healthy individuals without hyperlipidemia (p < 0.05)." (PMID 41583468, 2025).
infarct (1 paper, 2021). "Moreover, TLR7 and TLR8 values have interacted with IL1β and IL6 levels, and the expression of TLR8 was associated with cerebral infarct volumes." (PMID 34200356, 2021).
irritable bowel syndrome (1 paper, 2019). Irritable bowel syndrome (IBS) is a chronic functional condition of the lower gastrointestinal (GI) tract characterized by abdominal pain or discomfort and disordered bowel habit (diarrhea, constipation, or fluctuation between the two). "TLR-8 is implicated in the pathogenesis of several disorders including oral lichenoid reactions, irritable bowel syndrome (IBS), rheumatoid arthritis, systemic sclerosis and asthma." (PMID 31867014, 2019).
ischemia (1 paper, 2015). A hypoperfusion of the BLOOD through an organ or tissue caused by a PATHOLOGIC CONSTRICTION or obstruction of its BLOOD VESSELS, or an absence of BLOOD CIRCULATION. "Our data has shown that IVIg not only prevented ischemia-induced increased expression levels of TLR2, TLR4 and TLR8 and attenuated its signalling cascades but also ischemia-induced cleavage of apoptotic protease caspase-3." (PMID 25886362, 2015). "Our data reveals that treatment with IVIg significantly prevented ischemia-induced increased neuronal expressions of TLR2, TLR4 and TLR8." (PMID 25886362, 2015).
joint disease (1 paper, 2014). "Further, the human TLR8 chimeras developed more significant disease in the kidney than the mice in the current report, and some TLR8 chimeras developed significant clinical and histologic evidence of joint disease." (PMID 25229618, 2014).
leishmaniasis (1 paper, 2014). Infectious disease that is transmitted through the bite of hematophagous female phlebotomine sand flies. "Most studies of TLRs in leishmaniasis have been done in the murine models, where expression of TLR2, TLR4, TLR7, TLR8 and TLR9 have been analyzed and related to disease outcome, together with other contributing factors such as Leishmania species and genetic background." (PMID 25397678, 2014).
lymph node metastases (1 paper, 2024). "Patients with high cytoplasmic TLR8 intensity in lymph node metastases had received more somatostatin analogue treatment compared to low intensity group (72.2% vs. 50.0%, p = 0.048)." (PMID 38709790, 2024). "Of the 95 lymph node metastases, analyzable samples were available for 70 (TLR1), 72 (TLR2), 77 (TLR4), 58 (TLR5), 76 (TLR6), 72 (TLR7), 76 (TLR8) and 70 (TLR9) cases." (PMID 38709790, 2024).